GSK3B (glycogen synthase kinase 3 beta)
Diseases named in the same sentence as GSK3B in open-access papers (continued):
Sharing a sentence is not in itself a finding about the gene and the disease.
lung carcinoma (continued). "Taken together, our results demonstrate that FBW7 functions alongside GSK3β to promote IGF2BP2 degradation, thus inhibiting the IGF2BP2-SLC7A5 feedback loop and impairing lung cancer radioresistance." (PMID 38281999, 2024). "For example, in osteosarcoma, TRIM22 can impact autophagy by modulating the ROS/AMPK/mTOR signaling pathway, while in lung cancer, it can influence epithelial‐mesenchymal transition through the AKT/GSK3β signaling pathway." (PMID 38468469, 2024). "On the other hand, there has been no report regarding the role of GSK3A in gastric cancer, although GSK3A was shown to promote the survival of lung cancer cells, and both GSK3A and GSK3B are abnormally activated in non‐type bladder cancer cells." (PMID 36520032, 2023). "MiR-196b must be significantly decreased in lung cancer to maintain tumor cell viability, migration, and invasion and EMT induction by TGF-β, PI3K/AKT/GSK3β, Smad, and JNK pathways, as Runx2 is a putative target of miR-196b." (PMID 36551878, 2022). "In lung cancer, some studies indicate that diosmetin can selectively induce cell apoptosis through ROS accumulation by disrupting the PI3K/Akt/GSK-3β/Nrf2 pathway and enhance the efficacy of paclitaxel in NSCLC cells." (PMID 35646118, 2022). "In lung cancer, highly expressed SOX9 promoted cell proliferation and inhibited apoptosis by activating Wnt/β-catenin signaling through phosphorylation of GSK3β." (PMID 35281088, 2022). "Zhou et.al indicated that Schwann cells activated the PI3K/AKT/GSK-3β pathway and augmented the expression of Snail and Twist in lung cancer cells through CXCL5/CXCR2 axis, thus promoting the EMT and metastasis of lung cancer." (PMID 36522730, 2022). "Our research demonstrated, for the first time, that ZSD possessed therapeutic effect on lung cancer and elucidated that the AKT/GSK-3β/β-catenin pathway was partially involved in its anticancer effect." (PMID 33777320, 2021). "Intriguingly, our previous study demonstrated that LKB1 regulates GSK3β phosphorylation through the LKB1–APC–GSK3β interaction and influences the activity of the Wnt signaling pathway in lung cancer." (PMID 33924999, 2021). "In lung cancer, miR-1246 promoted migration, invasion, and EMT by regulating the Wnt/β-catenin pathway through directly targeting GSK-3β/β-catenin, which partly contributed to metastasis." (PMID 34112884, 2021). "The first mechanism involves enhanced GSK3β/β-TrCP-dependent degradation of NRF2 through activation of the AMPK/mTOR signaling pathway, and thereby triggering ferroptosis selectively in lung cancer cells." (PMID 34093872, 2021). "In present research, ARHGAP10 can decrease the expression levels of constituents of PI3K/Akt/GSK3β pathway and subsequently downregulated EMT biomarkers expression in lung cancer." (PMID 34174897, 2021). "In the current work, we demonstrated that BHGJT inhibited lung cancer growth by inducing cell cycle arrest via the downregulation of CDK4 and Cyclin D1 and apoptosis via the AKT/GSK3β/β-catenin signaling pathways." (PMID 34659548, 2021). "Then, the activation of the AKT/GSK-3β pathway by SC-79 partially abolished the effect of ZSD on inducing apoptosis and on suppressing cell migration and invasion in lung cancer cells." (PMID 33777320, 2021). "It was demonstrated that in lung cancer, OLA1 modulated EMT through GSK3β/Snail/E-cadherin, thereby modulating the invasion and metastasis of lung cancer." (PMID 35111070, 2021). "In lung cancer, HOXA4 was downregulated and inhibited the cell growth by promoting the transcription of GSK3β, thereby inhibiting Wnt signaling." (PMID 33479226, 2021).
lung carcinoma (continued). "Activation of the ERK/GSK-3β/β-catenin pathway following IL-17RB stimulation also promotes the invasion and the migration of H441 and CL1-0 human lung cancer cells in vitro." (PMID 32373132, 2020). "In lung cancer, DGCR5 bound to miR-1180 to suppress AKT, GSK-3β, and β-catenin expression, therefore suppressing the capacity of H520 and H1299 lung cancer cells to proliferate, migrate and invade." (PMID 33085646, 2020). "Therefore, our results suggest that combined treatment with GSK-3β inhibitor and conventional chemotherapy may be a promising approach to overcome environment-mediated drug resistance and for the treatment of EndMT-related disorders in lung cancer." (PMID 30709379, 2019). "Here, we investigated Zbed3's ability to promote lung cancer cell proliferation and invasion and the involvement of the Axin/TPC/glycogen synthase kinase 3β (Gsk‐3β) complex to the response." (PMID 30417576, 2019). "We first assessed expression of several Zbed3 and Wnt signalling molecules, including Axin, GSK‐3β, and β‐catenin in A549 and NCI‐H1299 lung cancer cells." (PMID 30417576, 2019). "Together, these data suggested that activation of the FAK/AKT/GSK3β pathway was required for Col XVII/laminin-5-mediated stabilization of Snail, and for maintenance of the EMT phenotypes in spheroid cultures of lung cancer cells." (PMID 29416721, 2018). "GSK-3β, inactivated by the MAPK and AKT signaling pathway, promotes the degradation of Slug and subsequently triggers EMT in lung cancer." (PMID 29921293, 2018). "Recently, GSK-3α and GSK-3β have been reported to be new kinase targets of tivantinib, which is a potent selective inhibitor of the receptor tyrosine kinase c-MET, in lung cancer cells." (PMID 27049759, 2016). "In summary, our results revealed that OLA1 is a novel endogenous suppressor of GSK3β, and through inhibiting the GSK3β/Snail/E-cadherin signaling, OLA1 positively regulates the EMT process in lung cancer cells." (PMID 26863455, 2016). "Our results suggest that fibulin-5 antagonizes Wnt signaling by inhibiting ERK and indirectly activating GSK3β to restrain β-catenin in the cytoplasm, which prevents MMP-7 and c-Myc expression and lung cancer cell invasion and proliferation." (PMID 25909283, 2015). "Together, these results indicate that fibulin-5 suppresses MMP-7 expression and lung cancer invasion through ERK inhibition and GSK3β activation, which in turn prevents β-catenin accumulation and nuclear translocation." (PMID 25909283, 2015). "Treatment with SMA inhibited A549 human lung cancer cell proliferation, and the IC50 value of SMA against serum- or GSK3β inhibitor-induced cancer cell proliferation was the lowest in A549 cells." (PMID 26544726, 2015). "On the other hand, it has been proposed that glycogen synthase kinase-3 beta negatively regulates Gli1 transcription factors cooperating with other kinases such as PKA and CK1s in lung cancer A549 cells." (PMID 22768056, 2012). "In non‐small cell lung cancer, emerging evidence has indicated that the antitumor mechanism of ARHGAP10 directly mediated the epithelial‐mesenchymal transition process via the PI3K/Akt/GSK3β pathway." (PMID 38230565, 2024). "In lung cancer cells, PD-L1 was also found to upregulate β-catenin through PI3K/AKT/GSK3β pathway." (PMID 35197539, 2022). "Regarding the mechanism, the AKT/GSK3β/β-catenin signaling pathway was responsible for growth arrest and apoptosis induced by BHGJT, and activation of autophagy was attributed to the AMPK/mTORC1/ULK1 signaling pathway in lung cancer cells." (PMID 34659548, 2021). "Moreover, we identified glycogen synthase kinase 3 beta (GSK3B) and interleukin-6 (IL-6) as novel potential therapeutic targets in colon and lung cancers, respectively, using organoids, 3D structures derived from the CSC-like cells." (PMID 33008481, 2020).
lung carcinoma (continued). "Besides, they blocked CXCL5 expression in SC significantly decreases the phosphorylation of AKT and GSK-3β in SC-treated lung cancer cells; PI3K inhibitor LY294002 blocks the activation of AKT/GSK-3β signaling in SC-conditioned lung cancer cells." (PMID 31921388, 2019). "Further investigations revealed that the inhibitory effect of PRL-3 on lung cancer cell motility may occur by suppressing the phosphorylation of AKT and GSK3β, which further decreases Slug and increases E-cadherin expression." (PMID 26967563, 2016). "Although the functional consequence of CREB activity by GSK-3 is not still clear, our study strongly suggests that CREB positively regulates GSK-3α, not GSK-3β, in lung cancer cells, thus providing a new concept of CREB-GSK-3α signaling." (PMID 27049759, 2016). "In lung cancer stem cells, EFEMP1 could suppress invasion and migration of lung adenocarcinoma cells by modulating the IGF1R/PI3K/AKT/GSK3β pathway." (PMID 27351229, 2016). "GSK3β seems to function independent of the β-catenin pathway in lung cancer, and recent studies of gastric, colorectal and hepatic cancers have yielded similar results." (PMID 24618715, 2014). "In particular, it has been shown that the IGF-IR/PI3K/GSK3β pathway mediates Oct-4 up-regulation as well as the formation of β-catenin/Oct-4/SOX2 complex, which is able to activate the Nanog promoter and maintain self-renewal of lung cancer stem-like cells." (PMID 24550888, 2014). "We find that downregulation of Cdc20 in non–small cell lung cancer (NSCLC) cells is sufficient to inhibit cell proliferation and growth in soft agar and to promote apoptosis, but not senescence, in a manner dependent on downregulation of securin following GSK-3β-mediated securin phosphorylation." (PMID 35988650, 2022). "In addition, the protein expression of GSK-3α was dramatically suppressed by CREB knockdown in all four lung cancer cell lines we tested but the protein level of GSK-3β was not changed by CREB knockdown." (PMID 27049759, 2016). "MSCs-derived exosomes promote EMT, invasion and migration of lung cancer cells, while silencing the expression of TGF-β1 in MSCs may inhibit MSCs-derived exosomes-mediated EMT formation of lung cancer by inactivating Smad2/3, Akt/GSK-3β/β-catenin, NF- κB, ERK, JNK and p38MAPK signaling pathways." (PMID 39679363, 2024). "Besides, anti-ENO1 mAb could attenuate lung cancer cell proliferation, invasion, and metastasis by inhibiting ENO1-mediated GSK3β activation and inactivating the Wnt pathway, and MET might restrain the survival of cancer cells, the stemness of CSCs and EMT by inactivating the Wnt/β-catenin pathway." (PMID 38515460, 2024). "GSK3β phosphorylates β-catenin and results in the degradation of β-catenin, which inhibits the activity of the Wnt signaling pathway Interestingly, it has been reported that the overexpression of FAM83A could interact with the Wnt/β-catenin signaling pathway in pancreatic cancer and lung cancer." (PMID 34641907, 2021). "Although this negative feedback might serve to regulate lung cancer progression via GSK-3β, CK1α, as the downstream rate-determining enzyme that sequentially phosphorylates β-catenin prior to GSK3β, remains to play a significant role in NIFK regulated β-catenin degradation." (PMID 26984280, 2016). "More importantly, CREB regulates the expression of GSK-3α but not GSK-3β, suggesting that there is a specific arm of CREB-GSK-3α signaling in lung cancer." (PMID 27049759, 2016). "We found that the mRNA level of GSK-3α, not the level of GSK-3β, was significantly downregulated by CREB siRNA in all lung cancer cell lines we tested (H1993, H1437, H1734, and A549)." (PMID 27049759, 2016). "Likewise, all the molecular and phenotypic (apoptosis) effects of the GSK-3β inhibitor should be demonstrated to occur in HUVEC, and not in the co-cultured lung cancer cells." (PMID 30709379, 2019). "Here, we first identified that GSK-3α, not GSK-3β, is regulated by CREB in lung cancer cells." (PMID 27049759, 2016).
pancreatic cancer (148 papers, 2009 to 2026). "It was found that the upregulation of nuclear GSK-3β is associated with dedifferentiation and NF-κB-mediated survival in pancreatic cancer, and MA significantly inhibited NF-κB and GSK-3β." (PMID 39863145, 2025). "CAP1 phosphorylated at S308/S310 regulatory site is associated with the increased activity of GSK-3β observed in pancreatic cancer." (PMID 36430630, 2022). "Treatment of pancreatic tumor xenograft mice with AR-A014418, a selective small molecule GSK-3β inhibitor, causes suppression of tumor growth." (PMID 34356465, 2021). "Glycogen synthase kinase-3 beta is a protein kinase implicated in the promotion and development of various cancers, including pancreatic cancer." (PMID 34356465, 2021). "In some cancers, such as human pancreatic carcinoma, GSK3β overexpression has been positively associated with tumorigenesis and cancer development." (PMID 34403222, 2021). "Particularly, in pancreatic cancer cells GSK3β pathway was associated with increased NFκB activity, increased cancer cell survival, tumor dedifferentiation and tumor resistance." (PMID 27602497, 2016). "At the same time, the connection between GSK3β and K-ras is still obscure, although it is important to clarify this connection since K-ras mutations occur in more than 90% of pancreatic cancers." (PMID 26556864, 2015). "Previous studies have shown that inhibition of GSK3β reduced the proliferation and survival of pancreatic cancer cells, which was associated with decreased cyclin D1 expression, Rb phosphorylation and secretion of matrix metalloproteinase-2 (MMP-2)." (PMID 26213494, 2015). "In pancreatic cancer, this is linked to Akt-regulation by galectin-3, which in turn modulates GSK-3β phosphorylation and β-catenin degradation by suppression of the β-catenin/Wnt signaling pathway." (PMID 21958686, 2011). "However, the mechanism underlying the anticancer effects of SFN on pancreatic cancer through GSK‐3β is unclear." (PMID 39632551, 2024). "However, the studies conducted so far to address the multifaceted role of GSK-3β in pancreatic cancer in vivo have mostly relied on loss-of-function approaches including knockout mice or GSK-3 inhibitors." (PMID 35646902, 2022). "Mutations in KRAS are the earliest events in pancreatic cancer initiation, and it is reported that expression of GSK-3b rises during progression of pancreatic cancer from preneoplastic lesions, suggesting a possible role for this oncogene in the observed overexpression." (PMID 34955846, 2021). "Thus, the decreased expression of Na +/K+-ATPase subunits, associated with the downregulation of the PI3K/AKT/GSK3β/β-catenin pathway, emerges as a mechanism by which nitroxoline induces antitumor effects in AsPC-1 pancreatic cancer cells." (PMID 32054977, 2020). "The chromatin modifier KDM6A, which has been implicated in the progression of squamous PDAC, is a common mutation shared by GSK3b inhibitor-sensitive PDCLs, and in keeping with reported findings, we observe squamous-like pancreatic cancer in these PDCLs despite the presence of GATA6." (PMID 32402285, 2020). "The GSK3β/β-catenin pathway has also been linked to pancreatic cancer." (PMID 26213494, 2015). "However, the novel findings of this study relate to the effects of GSK3β inhibition on the invasive ability and phenotype of pancreatic cancer cells and on their susceptibility to gemcitabine and radiation." (PMID 23408967, 2013). "Given the systemic pathology caused by aberrant GSK3β activity in glucose intolerance and chronic inflammation, GSK3β inhibition may decrease the risk of developing pancreatic cancer by improving these conditions." (PMID 24212624, 2011).
pancreatic cancer (continued). "Disrupting STYK1-β-catenin or STYK1-GSK3β interaction significantly inhibits GSK3β sequestration, subsequent Wnt/β-catenin signaling, and pancreatic cancer development." (PMID 40588478, 2025). "Some studies have verified that GSK-3β induces radioresistance in pancreatic cancer cells via the β-catenin mechanism." (PMID 40078194, 2025). "MA exhibited apoptosis induction in pancreatic cancer cells by inhibiting glycogen synthase kinase-3 beta (GSK-3β) and NF-κB signaling." (PMID 39863145, 2025). "In spite of the fact that the role of GSK-3β in cancer cells as a pro-oncogenic or suppressor protein is debatable, it has been agreed that GSK3-β is a pro-tumor protein and a good candidate for the targeted treatment of pancreatic cancers." (PMID 40649990, 2025). "For example, β-sitosterol dramatically suppressed G0/G1 phase arrest, Bcl-2 expression, and NF-kB and Akt/GSK-3β activity, while increasing Bax expression in pancreatic cancer to prevent cancer progression." (PMID 40487864, 2025). "In this study, we examined the anticancer effects of SFN in human pancreatic cancer cell line Mia PaCa‐2 and evaluated its molecular mechanisms with respect to the GSK‐3β‐related pathway." (PMID 39632551, 2024). "Over the past two decades, numerous studies have produced evidence of the pivotal role of glycogen synthase kinase (GSK)3β in the progression of over 25 different cancer types, including pancreatic cancer." (PMID 38318525, 2024). "Glycogen synthase kinase 3β (GSK‐3β), a serine/threonine kinase, is a critical player in pancreatic cancer progression, influencing tumor growth, metastasis, and resistance to therapy." (PMID 39632551, 2024). "Most studies on pancreatic cancer have demonstrated that the deregulated GSK3β sustains tumor cell survival, immortalization, and proliferation - common and fundamental features that engender therapy resistance in nearly all cancer types." (PMID 38318525, 2024). "Pancreatic cancer cell lines have decreased phosphorylation (Ser9), suggesting that GSK‐3β is largely in an activated state in PDAC to drive various protumorigenic processes." (PMID 39632551, 2024). "GSK‐3β promotes pancreatic cancer, including the regulation of cell proliferation, apoptosis, epithelial‐mesenchymal transition (EMT), and stemness." (PMID 39632551, 2024). "GSK3β potentially functions as a molecular hub that wires chemoresistance, tumor invasion, and cancer stemness phenotype, thereby aggravating pancreatic cancer towards the incurable/devastating disease stage." (PMID 38318525, 2024). "In keeping with this finding, one study reported that overexpression of LZTS1 upregulates the activity of the AKT/GSK‐3β signalling pathway in pancreatic cancer cells." (PMID 39023696, 2024). "In this review, we synthesize the current knowledge on the pathological roles of aberrant GSK3β in supporting tumor cell proliferation and invasion, as well as its contribution to gemcitabine resistance in pancreatic cancer." (PMID 38318525, 2024). "Collectively, GSK3β potentially functions as a molecular hub that wires chemoresistance, tumor invasion, and cancer stemness phenotype, thereby aggravating pancreatic cancer towards the incurable/devastating disease stage." (PMID 38318525, 2024). "•Metavert is a first-in-class dual inhibitor of GSK3-β and histone deacetylase which has been shown to be an effective therapy for pancreatic cancer in preclinical studies." (PMID 39217851, 2024). "It is conceivable that the respective mechanisms responsible for chemoresistance and tumor invasion share GSK3β as a common trigger for both malignant properties in gemcitabine-resistant pancreatic cancer." (PMID 38318525, 2024). "If future studies provide a direct relationship between tolerant anti-tumor immunity and the acquisition of chemoresistance, it will enhance the opportunity to combat chemoresistance in pancreatic cancer by targeting GSK3β." (PMID 38318525, 2024).